CRP (C-reactive protein)
Diseases named in the same sentence as CRP in open-access papers (continued):
Sharing a sentence is not in itself a finding about the gene and the disease.
abscess (continued). "Based on our data, CT should be performed around d 5 in case of suspicion of residual abscess if the CRP is above 10.0 mg/dL." (PMID 40046517, 2025). "In the internal validation, the AUCs of high CRP (0.70, 95 % CI 0.66–0.75), large abscess diameter (0.68, 95 % CI 0.44–0.91), RPE (0.73, 95 % CI 0.60–0.85), and risk score (0.83, 95 % CI 0.69–0.96) were comparable to those from the initial ROC analysis." (PMID 40236980, 2025). "A negative correlation was observed between the HALP score and length of hospital stay (r = −0.293, p < 0.01), abscess dimensions (height: r = −0.271; length: r = −0.267, p < 0.01), and CRP levels (r = −0.222, p < 0.01)." (PMID 40686698, 2025). "In contrast, the HALP score demonstrated significant negative correlations with hospital stay (r = −0.293, p < 0.01), abscess size (r = −0.271 for height, r = −0.267 for length, p < 0.01), and CRP levels (r = −0.222, p < 0.01)." (PMID 40686698, 2025). "This cohort study compared the effectiveness of three prophylactic antibiotic regimens in reducing a range of infection-related outcomes, including infection markers (ESR, CRP), wound colonization, clinical infections, fever, cellulitis, and abscess formation." (PMID 40841631, 2025). "Risk factors for septic metastases include septic shock at admission, low platelet count, low albumin, high levels of C-reactive protein (over 200 mg/L), and abscesses larger than 6 cm, as reported in a case-controlled study in Singapore." (PMID 40564854, 2025). "Key aspects of this case include the careful monitoring of CRP levels and renal function, adjustments in antibiotic regimens, and the importance of regular imaging to track the progress of the abscess." (PMID 39310602, 2024). "It outperformed C-reactive protein (CRP) in predicting severe abscesses with an AUC of 0.90 compared to 0.74 for CRP." (PMID 39410567, 2024). "CRP has the potential to be sensitive in identifying appendiceal perforation and the formation of abscesses." (PMID 38883094, 2024). "Seven days after drainage of the abscess his serum C-reactive protein had reduced to 28.6 mg/dL, and he was discharged." (PMID 38818095, 2024). "On further evaluation, all patients showed increased C-reactive protein in blood tests, and the location of the fascial space abscess was confirmed by enhanced computed tomography images." (PMID 38172867, 2024). "IE-aHF was also associated with the secondary endpoint of all-cause death as alongside the levels of CRP at admission, procalcitonin peak, LVEF, the presence of abscess, and prosthetic detachment." (PMID 38786960, 2024). "Increased CRP is a good indicator of appendiceal perforation or abscess formation in adult patients." (PMID 36900066, 2023). "Briefly, age, median WBC count, CRP level, and maximum abscess diameter were comparable between the two treatment groups." (PMID 37987979, 2023). "Sinuses and abscesses, located in the anterior sites, are more frequent than nodules; furthermore, elevated serum levels of IL-1, C-reactive protein, IL-17 and IL-6 were found." (PMID 37484864, 2023). "Conversion rates were increased in the presence of previous upper midline abdominal surgery, as shown in a recent prospective study and in advanced ACC with high CRP, gangrene or an abscess." (PMID 38066631, 2023). "Compared with adults, children had lower C-reactive protein, but a similar proportion of them had an abscess, and abscess size and rate of surgery were similar." (PMID 35184213, 2022). "Radiographic characteristics (e.g. multiple diverticula, more than one abscess), previous recurrent episodes, laboratory data (e.g. C-reactive protein), smoking, long hospital stay, and the use of steroids were noted across different studies." (PMID 36320045, 2022). "In 307 patients with MRI edema patterns and clinical data available, LOS was predicted by CRP (p < 0.001), ME (p = 0.012), and maximal abscess diameter (p < 0.001) (model 3)." (PMID 34331114, 2022).
abscess (continued). "The factors best predicting a severe clinical course were mediastinal involvement of the abscesses and the initial CRP and PCT values." (PMID 34160666, 2022). "Blood hemoglobin, CRP serum level, and abscesses on hip MRI were assessed before and two months after treatments." (PMID 36578841, 2022). "• Maximal abscess diameter, RPE, and C-reactive protein (CRP) were independent predictors of the need for intensive care unit (ICU) treatment, and maximal abscess diameter, ME, and CRP were independent predictors of length of hospital stay." (PMID 34331114, 2022). "After two months of treatment, blood hemoglobin and serum CRP levels returned to normal, and the intra-articular abscess disappeared." (PMID 36578841, 2022). "The expression of lncRNA NEAT1 was related to segments of the lesions, paraspinal abscesses, anti-TB treatment, drug resistance, interleukin-6 (IL-6), C-reactive protein (CRP), and erythrocyte sedimentation rate (ESR)." (PMID 35465262, 2022). "In this study, we found that a higher CRP level or abscesses in the anterior visceral and retropharyngeal spaces were the highest risk factors for mediastinal abscessation." (PMID 36556959, 2022). "Children had significantly lower CRP than adults, despite having similar rates of abscess formation." (PMID 35184213, 2022). "In patients with infection, increased white-blood-cell (WBC) and C-reactive protein (CRP), and/or abscess formation would be expected." (PMID 33350297, 2021). "Previous studies have shown that a high CRP is indicative of severe disease complications (perforations, abscesses, and fistula) in CD, whereas in UC it is correlated with disease activity and severe symptoms but not with histologic inflammation." (PMID 34834482, 2021). "Surprisingly, the one-stage group had higher CRP levels and a higher proportion of patients with abscess, sinus, draining wound, or fistula, a clinical presentation that often favors the 2-step surgery." (PMID 33178708, 2020). "In the current study, in addition to complete blood cell count, ESR, and CRP, neck plain radiographs, CT scan, MRI, and ultrasonography were performed for the diagnosis of abscess." (PMID 31554516, 2019). "Patients in the one-stage revision group seemed to have severe PJI at presentation compared with the two-stage group, given their higher levels of circulating CRP and higher proportion presenting with an abscess, sinus, draining wound, or fistula." (PMID 29623671, 2018). "Further effects of EEN were a significant decrease in CRP levels, surgical complications (8% vs. 32%) and infectious complications (abscess, collection, or leak, 3% vs. 20%)." (PMID 28587182, 2017). "Then, we compared the levels of albumin, erythrocyte sedimentation rate (ESR), and C-reactive protein (CRP) at abscess diagnosis and at operation in both groups of patients who underwent surgery later." (PMID 28947899, 2017). "Patients with abscesses greater than 5 cm were more likely to have a delayed clinical response—either remaining symptomatic or had an elevated C-reactive-protein (CRP) at 4 weeks of treatment." (PMID 29312894, 2017). "Actually, a number of studies, which included subjects at time of surgery, have indicated CRP is sensitive (83% to >90%) for detecting appendiceal perforation and abscess formation, which are both more commonly found in children." (PMID 26859663, 2016). "The presence of local signs (warmth, redness, swelling and tenderness), US signs (abscess) and laboratory signs (elevated CRP) of surgical site infection persuaded us to schedule prompt reoperation for ID." (PMID 24916148, 2015). "We have also shown that laboratory findings, especially regarding leucocytosis, C Reactive Protein and hemoglobin, were identical for large and small abscesses." (PMID 23951372, 2013).
abscess (continued). "Five days later, because of the remaining fever and biological signs (leukocytes of 16000/mm3 and a CRP count 60 mg/l), ultrasonography examination was practiced and showed multiple abscesses with one major abscess (6,5 × 8 cm)." (PMID 20946659, 2010). "Despite targeted meropenem therapy based on antimicrobial susceptibility testing, the abscess failed to regress and C-reactive protein levels continued to rise." (PMID 41600693, 2026). "Fever, abscess size and CRP levels were predictive of medical treatment failure in our study." (PMID 40162547, 2025). "DeLong’s test showed that the risk-score model significantly outperformed the individual predictors: CRP (AUC=0.73, 95 % CI 0.66–0.80, p = 0.001), abscess diameter (AUC=0.72, 95 % CI 0.64–0.80, p < 0.001), and RPE (AUC=0.71, 95 % CI 0.65–0.77, p < 0.001) (p-values for AUC comparisons)." (PMID 40236980, 2025). "A risk model incorporating RPE, abscess size, and CRP showed moderate accuracy and high negative predictive value for ICU admissions, supporting MRI’s role in acute neck infections." (PMID 40236980, 2025). "The study suggested that integrating CRP and other inflammatory markers, particularly in cases with complications such as abscess or peritonitis, could enhance its predictive power." (PMID 40282883, 2025). "Additionally, higher CRP levels correlated with both the length of hospital stay (r = 0.190, p < 0.01) and abscess size (r = 0.134 for height, p = 0.051; r = 0.147 for length, p < 0.05)." (PMID 40686698, 2025). "In this case, abscess-related infection symptoms (fever, significantly elevated white blood cells and CRP, and empyema abdominal cavity) are one of the outstanding manifestations, which increases the complexity of preoperative diagnosis of IAF and easily misleads the diagnostic direction." (PMID 41278299, 2025). "Moreover, in this type of case, the analysis of biochemical parameters, including inflammatory markers such as CRP, procalcitonin or white blood cell, has limited value in differentiating the etiology of perforations, abscesses or fistulas." (PMID 40217777, 2025). "CRP’s lowest mean net benefit when used alone (0.099) and its inability to provide clinical utility at high threshold values reflect its nature as a nonspecific acute-phase reactant that can be elevated in both abscess and cellulitis." (PMID 41153226, 2025). "C-reactive protein and fever show significant differences between abscesses and ascites." (PMID 39036172, 2024). "Limited studies, including subjects at the time of surgery, suggest that CRP may be more sensitive (83% to >90%) in detecting appendiceal perforation and abscess formation, conditions more commonly found in children." (PMID 37509519, 2023). "CRP levels less than 50 mg/L may suggest acute uncomplicated diverticulitis, however CRP levels greater than 200 mg/L may signal complications such as perforation with peritonitis or abscesses." (PMID 36978310, 2023). "The need of surgical interventions in children with OM lacks consensus as for need, timing and extent, but is to be considered in case of a scarce response to antibiotics, with persistent fever, symptoms and/or elevated CRP, presence of abscesses or suspicion of other complications." (PMID 36911022, 2023). "In addition, high CRP values, high abscess volume, and SLSE significantly predicted deep extension in a multivariate statistical model." (PMID 36617619, 2023). "Compared with the group that received non-total excision, the group that received total excision had higher values for WBC count, band cell proportion, and C-reactive protein level, with a greater percentage of segmented neutrophils and an increased proportion of extensive abscesses (both p = 0.06)." (PMID 37512105, 2023).
abscess (continued). "Multivariable logistic regression analysis indicated that the presence of abscess and presence of free fluid in the right upper quadrant (RUQ FF) on initial imaging and C-reactive protein (CRP) level >12 at admission, were independently associated with a longer stay." (PMID 35463908, 2022). "Also listed are the available data on abscess-related symptoms and laboratory parameters (c-reactive protein, leukocytes) at baseline, and imaging techniques used in diagnostic evaluation." (PMID 36556042, 2022). "In our patient, the development of discitis could have been avoided if the abscess had been surgically drained when elevated CRP levels were noted." (PMID 35610493, 2022). "Patients who required ICU treatment had higher CRP (188 vs. 111, p < 0.001), larger maximal abscess diameter (5.4 vs. 3.1 cm, p <0.001), and thicker RPE (5.4 vs. 4.5 mm, p = 0.050), whereas other clinical and laboratory variables were not significantly different." (PMID 34331114, 2022). "Additionally, despite multiple abscesses, the patient’s C-reactive protein was only minimally elevated." (PMID 35382862, 2022). "The association between longer stay and the findings of abscess and RUQ FF on initial imaging along with an elevated CRP may provide a useful tool in identifying those children at risk for worse outcomes." (PMID 35463908, 2022). "Increased WBC and CRP levels could be markers to estimate the severity of appendiceal inflammation and/or abscess formation." (PMID 33427959, 2021). "Presence of abscess formations > 1 cm significantly correlated with CRP values." (PMID 34189654, 2021). "The significant factors were age ≥40, duration of symptoms >24 hours, body temperature ≥37.3°C, high levels of CRP, findings in CT scan (appendix diameter ≥10 mm, stranding of the adjacent fat, presence of fluid collection, and suspicion of abscess or perforation)." (PMID 34314464, 2021). "CRP assessment can detect leak and abscess with a high level of sensitivity and specificity." (PMID 32696145, 2020). "Optimal cutoff points for white blood cell count (WBC) (14.8 × 109/l, rounded to 15.0 × 109/l), CRP (174 mg/l, rounded to 175 mg/l), and abscess size (47 mm, rounded to 50 mm) were determined by maximum value of Youden’s index for receiver operating characteristic (ROC) curve." (PMID 31320921, 2019). "In addition, the one-stage revision group had higher median levels of baseline blood circulating CRP and a higher proportion of patients presenting with an abscess, sinus, draining wound, or fistula before revision." (PMID 29623671, 2018). "In this work, secondary infections incidence was significantly associated to higher levels fibrinogen, alanine transaminase and C-reactive protein, suggesting these laboratorial markers as auxiliary tools for the diagnosis of secondary infections allied to clinical signs of cellulitis and abscesses." (PMID 28692641, 2017). "ESR and CRP can’t return to normal within 2–4 weeks after chemotherapy, because of abscesses persisting, but TB toxicity symptoms may be relieved." (PMID 28407019, 2017). "A differential diagnosis also worth mentioning is the inflammatory subtype of undifferentiated pleomorphic sarcoma, which mimics an abscess clinically and presents with constitutional symptoms including fever and malaise in addition to an elevated CRP and erythrocyte sedimentation rate (ESR)." (PMID 27923374, 2016). "For example, the same intraabdominal fluid collection on a CT scan may be classified as abscess if the CRP is high, but as ascites if the CRP is low." (PMID 25935447, 2015). "The presence of local signs (warmth, redness, swelling, tenderness and fluid discharge), US signs (abscess) and laboratory signs (elevated CRP) of surgical site infection convinced us to schedule immediate irrigation and debridement (ID) within 1 week from complication onset." (PMID 24916148, 2015).
abscess (continued). "Switching to an oral antibiotic regimen after two weeks intravenous treatment may be safe, provided that CRP has decreased and epidural or paravertebral abscesses of significant size have been drained." (PMID 24767169, 2014). "Furthermore, a rise in inflammatory markers like CRP and ESR increases the likelihood of an underlying chronic prostatitis/abscess formation." (PMID 23762676, 2013). "This was in a 3-year-old girl where operative exploration showed appendicular abscess, because of fever persisting with a leukocytes of 15600/mm3 and a CRP count 170 mg/l, abdominal ultrasound was practiced and showed a sub-phrenic abscess (43 × 21 mm) which was immediately drained." (PMID 20946659, 2010). "Furthermore, RPE volume correlated positively with LOS, CRP, and maximal abscess diameter." (PMID 41729484, 2026). "Conversely, false negatives are also possible—for example, a well-localized infection or abscess might not cause a dramatic systemic CRP response in certain patients." (PMID 41153812, 2025). "Numerous other factors, including laboratory parameters (C-reactive protein > 50 mg/L), CT features (nonsclerotic endplate erosions), and magnetic resonance criteria (paravertebral/epidural abscess formation), appeared to be associated with positive pathogen detection." (PMID 37297888, 2023). "Besides, in patients with DP drainage, the time for reduction in the diameter of the abscess to half was shorter, the rate of decrease in c-reactive protein levels was more rapid (suggesting faster resolution of inflammation) and the size of the abscess at the time of catheter was smaller." (PMID 36713673, 2022). "However, CRP levels, and abscess numbers were different between the groups." (PMID 32677915, 2020). "In murine models, PIX (30 mg/kg i.v.)reduced inflammatory markers (CRP, IL-6, TNF-α), abscess size, and bacterial loads to levels comparable with ΔhisD infection." (PMID 41294339, 2026). "Clinical parameters (such as smoking history, C-reactive protein (CRP), erythrocyte sedimentation rate (ESR), immunosuppressive therapy) and IUS parameters (such as bowel wall thickness (BWT), HMF, abscess/fistula) were compared." (PMID 41989673, 2026). "Significant differences (p < 0.05) were observed between EPR and non-EPR groups for clinical factors (smoking history, elevated preoperative CRP/ESR, postoperative immunosuppression) and IUS parameters (HMF, BWT, and abscess/fistula)." (PMID 41989673, 2026). "These volumes were correlated with clinical variables, such as the need for intensive care unit (ICU) admissions, C-reactive protein (CRP) levels, maximal abscess diameter, and length of hospital stay (LOS)." (PMID 41729484, 2026). "In vivo, pixantrone (30 mg/kg) decreased serum CRP, IL-6, and TNF-α levels while diminishing abscess sizes and splenic bacterial loads (P < 0.05 vs. untreated)." (PMID 41294339, 2026). "Those admissions that had early intervention had larger abscesses and higher inflammatory markers (WCC, neutrophils, CRP) than those who had initial medical management, suggesting that more severe disease was present in that group." (PMID 40162547, 2025). "Demographics, comorbidities, laboratory markers (CRP, ESR, ALP, albumin), radiological findings (abscess presence, anatomical location, claw sign), prior antibiotic use, and microbiological results were analyzed." (PMID 41010981, 2025). "We evaluated both clinical outcomes (such as colonization, clinical infection, fever, cellulitis, deep infection, and abscess formation) and laboratory parameters (ESR and CRP levels) over a six-month follow-up period." (PMID 40841631, 2025). "Regarding the secondary endpoint of death from any cause, significant differences between groups emerged for the following variables: IE-aHF, CRP at admission, procalcitonin peak, LVEF, abscess, and prosthetic detachment." (PMID 38786960, 2024). "Inflammatory markers such as CRP and PCT showed significant variations based on bacterial etiology and abscess origin." (PMID 39403639, 2024).